GSK3B (glycogen synthase kinase 3 beta)
Diseases named in the same sentence as GSK3B in open-access papers (continued):
Sharing a sentence is not in itself a finding about the gene and the disease.
cancer (continued). "GSK3β has an important theranostic potential in pathologies where stem cells are deregulated, such as inflammation and cancer." (PMID 33498808, 2021). "PI3K/Akt not only leads to the activation of both GSK3β and mTOR but also has been found upstream of NF-κB activation in different cancers, and the NF-κB pathway is believed to be a target of Akt." (PMID 34380537, 2021). "In this study, we sought to profile the proteomic and phenotypic effects of GSK3β in Wnt/ β-catenin-dependent cancer cells to identify other GSK3β-dependent pathways and processes in addition to canonical Wnt signalling." (PMID 34739494, 2021). "We and others have found that natural compounds and their derivatives are potential drugs to kill cancer stem cells through GSK3β inhibition." (PMID 33498808, 2021). "Pharmacological inhibition or genetic knockdown (KD) of GSK-3β sharply antagonizes erastin-initiated ferroptosis in cancer cells." (PMID 34732689, 2021). "In order to validate GSK-3β as a cancer target, we characterized the effects of its inhibitor, CHIR99021, on VA-ES-BJ cell line." (PMID 34681807, 2021). "Molecular studies in cancer showed that Wnt signaling controlled the activity of the mTOR pathway via GSK3β phosphorylation of TSC2, promoting the inhibitory function of TSC2 on mTOR activity." (PMID 34358226, 2021). "GSK3β activity is a key marker for inflammatory and cancer diseases allowing adjusted therapy to sex, age and metabolic status of patients." (PMID 33498808, 2021). "This study highlights a potential therapeutic design to cancers by targeting the GSK-3β and ferroptosis." (PMID 34732689, 2021). "GSK3β phosphorylates a series of substrates, including β-catenin and Myc, resulting in degradation and/or inactivation, and thereby inhibiting cancer cell proliferation and metastasis." (PMID 34433808, 2021). "GSK3β is highly inactivated in cancers, and GSK3β-mediated phosphorylation of Slug facilitates Slug protein ubiquitylation and degradation." (PMID 34595179, 2021). "GSK-3β possesses distinct sites of phosphorylation, including Ser9, as well as Tyr216, which play distinct roles in distinct kinds of cancers." (PMID 33762939, 2021). "Herein, we presume that GSK-3β inhibition leads to DNA repair disruption and plays a significant role in sensitizing of cancer cells toward 5-FU and Oxaliplatin." (PMID 34955846, 2021). "Previous reports have clearly established the role of Wnt/GSK3β/β-catenin signaling in various cancers." (PMID 33500726, 2021). "Such pre-leukemic stem cells with high GSK3β activity have been described in transition to cancer stem cells with deregulated β-catenin." (PMID 33498808, 2021). "Since AKT-mediated phosphorylation inhibits GSK-3β activity for β-TCRP-dependent degradation of NRF2, activated PI3K/AKT signaling is often associated with NRF2 activation in multiple types of cancers." (PMID 35155201, 2021). "This study highlights a potent therapeutic design for cancers by targeting the GSK-3β–iron metabolism–ferroptosis axis." (PMID 34732689, 2021). "Some other studies are showing that these molecules (β-catenin, GSK-3β, AKT, and ILK) are involved in normal biological events, and their overexpression is associated with cancer." (PMID 35317111, 2021). "GSK3B was reported to promote GBM cancer development and progression and has emerged as a target for drug development." (PMID 33671112, 2021). "Multiple roles have been suggested for GSK3B in different cancers, and even after years of study they remain complex and controversial." (PMID 35096583, 2021). "There are key interactions between NF-κB and GSK-3β, which result in important loops that stimulate the growth of certain cancers." (PMID 33917370, 2021). "Phosphorylation of its substrate GSK-3β can inhibit the translocation of Bax and the degradation of Bcl-2, leading to apoptosis inhibition of cancer cells." (PMID 34497528, 2021). "For example, GSK-3β protein was reportedly overexpressed in human ovarian, colon, and pancreatic cancers." (PMID 34966427, 2021).
cancer (continued). "Recent reports have suggested that GSK-3β is a positive regulator of cancer cell proliferation and survival, thus, providing further support for GSK-3β as a therapeutic target in cancer." (PMID 33503871, 2021). "Justicidin A, a well-defined arylnaphthalide lignan, has shown anti-cancer activity and can exert neuroprotective effects by inhibiting the hyperphosphorylation of the protein tau and regulating the activities of GSK-3β and AMPK50." (PMID 34433871, 2021). "GSK3β has been found activated in pathologies such as inflammation and cancer where the deregulation of adult stem cells plays a critical role." (PMID 33498808, 2021). "Taken together, our data suggested that inhibiting autophagy using 36-077, a PIK3C3/VPS34 inhibitor, along with 5-FU treatment, has a profound effect on the GSK-3β/Wnt/β-catenin signaling to inhibit cancer stem cells." (PMID 33946505, 2021). "The in silico molecular docking study was also performed recruiting GSK-3β as the promising cancer target receptor." (PMID 33503871, 2021). "In cancer and developmental biology studies, lithium chloride is often used to activate Wnt signaling through its actions on GSK3β." (PMID 34358226, 2021). "From a further bioassay, it was found that secalonic acid D influenced the GSK-3β/β-catenin/c-Myc pathway, thereby arresting the cancer cell cycle and inhibiting the proliferation of cancer cells." (PMID 34832926, 2021). "Taken together, our study not only provided a supporting evidence for the anti-metastasis activities of CP against HBV-associated HCC, but it also addressed the novel role of Cav-1 in mediating the Akt/GSK3β/β-catenin axis during advanced cancer stages." (PMID 34168559, 2021). "The abnormal AKT/GSK3β/Snail signaling has already been identified to relate with the progression of tumors in several cancers, including GC." (PMID 34546849, 2021). "The AKT/GSK3β/CTNNB1 signaling pathway is critical for the progression of several cancers, including HCC." (PMID 34950583, 2021). "Recently, the induction of Wnt/β-catenin signaling via PI3K/Akt/GSK3β cascade has been proposed to drive drug resistance in cancer cells." (PMID 34349823, 2021). "Our findings identified a novel regulatory mechanism of GSK3β stabilization with PGK1 as a co-chaperone of Hsp90, and emphasized the potential of selecting Hsp90 inhibitors with GSK3β stabilization for more effective cancer treatments." (PMID 34403222, 2021). "Activation of AKT/GSK‐3β signalling can lead to the accumulation and translocation of β‐catenin, which facilitates cancer malignancy." (PMID 34121323, 2021). "The canonical Wnt pathway directly regulates cancer EMT programs via activation of the β-catenin/TCF complex-regulated Axin2/GSK3β/Snail cascade." (PMID 34572856, 2021). "In echoing the important roles of CK1 and GSK3β-mediated PDK1 phosphorylation and degradation, patients-associated mutations S390L, S394L and S398L were identified in cancer patients." (PMID 34353330, 2021). "For example, in the C-T network, ICT, kaempferol and sitosterol target proteins associated with inflammation, cancer cell apoptosis and migration in the TME, such as COX2, IL-6, GSK3β, CDK2 and NOS3." (PMID 33460401, 2021). "Recent evidence suggests that GSK-3β stimulates autophagy through phosphorylation of Ulk1 at Ser405 and Ser415 in neurons and cancer cells." (PMID 34778891, 2021). "EGCG can inhibit GSK3β degradation and phosphorylation while promoting GSK3β expression, leading to a decrease in the amount of β-catenin in cancer cells." (PMID 33995644, 2021). "The alkaloid koenimbin found in M. koenigii was shown to extend pro-apoptotic activities in MCF-7 cancer cells by inhibiting glycogen synthase kinase-3 beta (GSK-3β)." (PMID 31991665, 2020). "The biological rationale for targeting GSK3β in the treatment of cancer is also discussed at length." (PMID 32503133, 2020).
cancer (continued). "Other studies have shown that upregulation of MRE11 expression through the GSK3β/β-catenin/LEF pathway leads to enhanced DSB repair efficiency in cancer cells." (PMID 33216839, 2020). "Targeting GSK3β for the treatment of diseases has raised concerns regarding the development and progression of cancer due to the promotion of proto-oncogenic pathways mediated by Wnt/β-catenin and Hh signaling." (PMID 32503133, 2020). "Herein, we also report the vital involvement of lncRNA RUNX1-IT1 in the repression of cancer stemness through modulating miR-632/GSK-3β/β-catenin cascades." (PMID 32024815, 2020). "Numerous studies have reported that the PI3K/AKT/GSK3β/β-catenin pathway is aberrant and promotes proliferation, migration and invasion in a wide variety of cancers." (PMID 31900208, 2020). "inhibit cancer growth through regulation of p85/Akt-dependent or GSK3β-related caspase-3-dependent apoptosis on a xenograft mouse model bearing murine T cell lymphoma (RMA) cell-derived cancers." (PMID 33628175, 2020). "This review will discuss preclinical and initial clinical results with GSK-3β inhibitors, highlighting the potential importance of this target in cancer immunotherapy." (PMID 32526891, 2020). "Recent studies have shown that GSK3β is overexpressed in several cancer cell types, and inhibition of GSK3β decreased cancer cell proliferation and survival." (PMID 32158616, 2020). "In summary, accumulating evidence defines GSK3β as a potential therapeutic target in cancer, thus encouraging the development of GSK3β inhibitors for cancer treatment." (PMID 32503133, 2020). "Members of the WNT signaling pathway, including GSK3β and WNT11, control migration, polarity, and fate during embryonic development and are widely implicated in human cancers." (PMID 32143304, 2020). "Cordycepin restrains the proliferation of cancer cells by triggering adenosine A3 receptors followed by the Wnt signaling pathway, including glycogen synthase kinase three beta (GSK3β) activation and cyclin D1 inhibition." (PMID 33628175, 2020). "GSK3β inhibition, including by O-GlcNAcylation, will therefore modulate both cancer cells and cytolytic cells." (PMID 33375613, 2020). "HSPA1L also partly affected stemness and EMT in cancer cells by regulating ALDH1 expression via β-catenin stabilization by the IGF1Rβ/AKT/GSK3β activation pathway." (PMID 32971893, 2020). "Taken together, this information provides a strong rationale for the targeting of GSK3β in the quest to cure cancer." (PMID 32503133, 2020). "Future studies on the role of GSK3β in normal and cancer SCs should; therefore, be aimed at elucidating the biological mechanisms that underlie selective eradication of CSCs." (PMID 32503133, 2020). "HSPA1L/integrin αV complex-associated IGF1Rβ activation intensified the EMT-associated cancer stemness and γ-radiation resistance through its downstream AKT/NF-κB or AKT/GSK3β/β-catenin activation pathway." (PMID 32971893, 2020). "Many literatures have reported that PI3K/Akt activation promotes the activation of GSK3β and then induces various diseases, including cancer, neurological diseases, and inflammatory diseases." (PMID 32832542, 2020). "Targeting MYH9 blocked HBX-induced GSK3β ubiquitination to activate the β-catenin destruction complex and suppressed cancer stemness and EMT." (PMID 32296025, 2020). "Several studies have reported that inhibition of GSK3β enhances the efficacy of chemotherapeutic agents and radiation in various cancer types." (PMID 32503133, 2020). "GSK3β is involved in many prevalent disorders, including psychiatric and neurological diseases, inflammatory diseases, and cancer, and regulates the nuclear export and degradation of Nrf2 (Beurel, Grieco & Jope, 2015; Jain & Jaiswal, 2007)." (PMID 32551202, 2020). "We also discussed the potential roles for GSK3β in sustaining the immune checkpoint machinery and IL-17/Th17 immunity, as well as in therapeutic targeting of K-ras mutant cancers." (PMID 32503133, 2020).
cancer (continued). "Instead, this review will focus on the critical roles that GSK3β has in cancer biology and treatment." (PMID 32503133, 2020). "Noticeably, the therapeutic potential of several inhibitors of the AKT and GSK3β signaling pathways have been extensively studied in the context of cancer." (PMID 32630830, 2020). "An important factor in cell growth signaling and apoptosis control, GSK-3β is a potential therapeutic target in cancer." (PMID 32526891, 2020). "Impairment of GSK3β function have been described in several disorders and diseasesincluding cancer, cardiovascular disease and neurological disorders such as Alzheimer’sdisease, bipolar disorders, and Huntington’s disease." (PMID 32130369, 2020). "With clinical trials of GSK3β inhibitors under way in the phase I space, an important question moving forward is the clinical effect of these drugs on cell types other than the cancer cells." (PMID 32850361, 2020). "Here, we review the evidence supporting aberrant GSK3β as a hallmark property of cancer and highlight the beneficial effects of GSK3β inhibition on normal cells and tissues during cancer therapy." (PMID 32503133, 2020). "Snail1 is essential for the invasion and metastasis of cancer cells, and its stability is regulated by glycogen synthase kinase 3 beta (GSK-3β)-induced ubiquitination 26-28." (PMID 32483465, 2020). "The PI3K/AKT/GSK3β signal axis and its downstream cell cycle regulation are the most prominent drug targets in cancer treatment." (PMID 33027592, 2020). "Previous research verified that MYPT1/Gsk3β is the critical substrate of NUAK1 kinase that protects cancer cells from oxidative stress." (PMID 32873786, 2020). "These early results hold considerable promise for the targeting of GSK3β in T-cell-mediated anti-cancer immunotherapies." (PMID 32503133, 2020). "In striking contrast, GSK3β expression in cancer cells is reduced in comparison to normal or pericancerous tissues, which correlates to clinical-pathological characteristics and a poor prognosis." (PMID 33339170, 2020). "GSK3β also renders cancer cells resistant to chemotherapy, ionizing radiation and some molecular targeted agents." (PMID 32503133, 2020). "ER stress also enhances glycogen synthase kinase-3 beta (GSK3β) expression, and GSK3β inhibition reverses the effects of miR-346 on ROS production, suggesting the role of Wnt signaling in regulating cancer progression through the miR-346/ROS/GSK3β axis." (PMID 35006436, 2020). "Glycogen synthase kinase (GSK)3β has emerged as a multipotent therapeutic target in various diseases including cancer." (PMID 32678196, 2020). "In various types of cancer, deregulation of the Wnt/β-catenin signaling pathway occurs almost invariably via mutations in APC gene, dysfunction of GSK3β, or mutations of β-catenin itself." (PMID 32758292, 2020). "Investigating the selective inhibition of GSK3α and GSK3β will be critical for elucidating the role that each paralog plays in ND and cancer." (PMID 33339170, 2020). "Consistent with the previous findings, MYH9 and β-catenin expression levels were elevated (P < 0.001 and P = 0.007, respectively), but GSK3β expression levels were decreased in HCC tissues in contrast to those in para-carcinoma tissues (P < 0.001)." (PMID 32296025, 2020). "Several downstream targets of AKT, such as GSK-3b, Bad, and NF-κB, are known to directly or indirectly regulate apoptosis in many cancers." (PMID 31086026, 2019). "Glycogen synthase kinase 3 beta (GSK3β) plays key roles in various cellular and physiological processes and exerts opposing effects depending on the type of cancer." (PMID 31001473, 2019). "In the cell cycle pathway, GSK3B, CDK2, and CDK1 are reduced by cisplatin in each cell line, and in cancer pathways, cisplatin reduces phosphorylation of GSK3B, AKT1, PDGFRa/b, PLCG1/2, and CDK2." (PMID 31929796, 2019).
cancer (continued). "Has2 gene disruption reduced the in vivo growth of aggressive cancer cells and attenuated pro-tumorigenic Akt/GSK3β/β-catenin signaling and cisplatin resistance." (PMID 31645543, 2019). "Having established that 2i broadly inhibits UHRF1 and DNMT1 expression in cancer cells, we next explored if GSK3β and/or MEK/ERK pathway were required for UHRF1/DNMT1 expression in cancer cells." (PMID 30696879, 2019). "GSK3-β was additionally demonstrated to induce cell proliferation and survival in cancer, a function that is related with its ability to regulate the transcriptional regulator NF-κB." (PMID 31362447, 2019). "Although GSK-3β had been shown to be important in the treatment of some cancers and the pathogenesis of fibrosis in other organs, its role in myofibroblast differentiation and the progression of PF has remained unclear until the present time." (PMID 31831767, 2019). "Multiple roles have been suggested for GSK3β in different cancers, and its importance has been controversial." (PMID 30845991, 2019). "We also observed DHT-mediated activation of Akt/GSK-3β signaling pathway which plays a central role in cancer progression." (PMID 31119584, 2019). "We further revealed that circGSK3β promoted ESCC cell migration and invasion via direct interaction with GSK3β and inhibiting GSK3β activity, providing a novel mechanism of circRNA in cancer progression." (PMID 31722716, 2019). "In the context of cancer treatment, GSK-3β is well known as a positive regulator of transcriptional activity of NF-κB6–8." (PMID 31882719, 2019). "As an upstream kinase of GSK3β, AKT is directly associated with the phosphorylation of GSK3β on Ser9, and its oncogenic mutations driving over-activation of PI3K/AKT pathway tend to result in excessive inactivation of GSK3β in various cancer cell lines." (PMID 31121982, 2019). "GSK3β is known to play a role in cancer and has been documented as having both cancer promoting and cancer inhibiting functions." (PMID 30854564, 2019). "Rab25 induces epithelial–mesenchymal transition and activates AKT/GSK-3β/Snail signaling to increase cancer cell invasion and metastasis." (PMID 30158579, 2018). "Here, we report that the anti-cancer activity of RS-PP-050 involves the inhibition of Wnt/β-catenin signaling via a GSK-3β-independent pathway." (PMID 29784906, 2018). "The same effect was observed in these cancer cell lines following depletion of GSK3β expression by treatment with a specific small interfering RNA (siRNA), whereby depletion efficiency was confirmed by immunoblotting." (PMID 29568361, 2018). "This is the first evidence showing that the anti-cancer activity of an andrographolide analogue is on the level downstream of GSK-3β toward the nucleus of Wnt signaling pathway." (PMID 29784906, 2018). "Phosphorylation of GSK3β on Tyr216 induces GSK3β activation and function, which is followed by its dephosphorylation on Ser9, though the role of GSK3β is controversial in cancer progression or apoptosis." (PMID 30201862, 2018). "In most human cancers the pro-survival kinase signaling pathway PI3K/Akt is activated accompanied by the inactivation of GSK3β.Hence the expression of PI3K and Akt in GAE treated cells was analyzed." (PMID 29558998, 2018). "In vitro experiments also showed that the LSD1 inhibitor SP2509 and the GSK3β inhibitor LY2090314 acted synergistically to induce cancer cell death." (PMID 29593255, 2018). "Natural products that target the PI3K/Akt/GSK-3β pathway promote autophagy to sensitize cancer cells to apoptosis." (PMID 30352996, 2018). "Further, our work also provides new insights into mechanisms for cancer cell mitosis, and reinforces this strategy for cancer treatments targeting GSK3β." (PMID 29568361, 2018). "Inactivation of GSK-3β, a primary kinase in the β-catenin multi-protein destruction complex, is frequently found in human cancers." (PMID 30068336, 2018).